INS (insulin)
Diseases named in the same sentence as INS in open-access papers (continued):
Sharing a sentence is not in itself a finding about the gene and the disease.
diabetes (continued). "Comparably, a board of Italian scientific societies reported that metformin could be used for diabetes in pregnancy as a second-line treatment or in addition to insulin, to reduce its dose, especially in obese women." (PMID 37798604, 2024). "Moreover, resveratrol is widely utilized in diabetes treatment, primarily for its roles in reducing blood sugar levels, enhancing insulin sensitivity, and preserving pancreatic beta cells." (PMID 39125368, 2024). "This might be explained by fundamental differences in insulin metabolism between both diabetes types." (PMID 38932803, 2024). "Some SNPs were associated with the known confounders (body mass index, glucose, diabetes, alcohol, smoking, cholesterol, triglycerides, high-density lipoprotein, low-density lipoprotein, blood pressure, insulin, and obesity), which were excluded from further analysis." (PMID 38671284, 2024). "Insulin treatment is the cornerstone of diabetes mellitus (DM) management in dogs." (PMID 38831362, 2024). "As expected, insulin AUC/iAUCs from the OGTT predicted the development of diabetes." (PMID 38987291, 2024). "The noted decline in search interest for islet cell transplantation could indeed be partly attributed to advancements in diabetes management technologies, such as insulin pumps and continuous glucose monitoring (CGM) systems." (PMID 38666804, 2024). "The beneficial effects of trigonelline on diabetes have been extensively documented, encompassing its capacity to reduce blood glucose and lipid levels, enhance insulin sensitivity index and insulin content, up-regulate antioxidant enzyme activity, and attenuate lipid peroxidation." (PMID 38725583, 2024). "Despite poor glycaemic control, there is a practice of increasing the dose of oral anti-diabetics or adding more drugs to the regimen due to the common perception that low endogenous insulin secretion is related to type 1 diabetes mellitus only and patient's poor compliance to injectables." (PMID 38654804, 2024). "Dietary interventions and lifestyle behavior modifications play critical roles in the management of diabetes and could reduce the need for medication and insulin therapies in certain scenarios for patients with diabetes." (PMID 39458437, 2024). "Indeed, vitamin D supplementation has been demonstrated to exert beneficial effects on glycemic levels, glucose tolerance, and insulin secretion in experimental models of diabetes and in humans." (PMID 38673723, 2024). "A low Disposition Index (DI, i.e. insulin secretion relative to insulin sensitivity) is an early marker of impaired β-cell function and, while reversible, may predict future development of diabetes." (PMID 38958831, 2024). "The same study also pointed to another factor affecting observed heterotaxy rates, namely diabetes, which may impact penetrance of heterotaxy phenotypes through physiologic factors such as exposure of the developing fetus to insulin." (PMID 38570875, 2024). "Diabetes mellitus, including Type 1 diabetes (T1D) and advanced Type 2 diabetes (T2D), remains a major global health challenge due to the destruction or dysfunction of insulin-producing β-cells." (PMID 39906747, 2024). "Diabetes mellitus is a serious, chronic disorder characterized by hyperglycemia that develops due to the inability of the pancreas to produce a sufficient amount of insulin or the failure of the body to effectively utilize the produced insulin." (PMID 39403648, 2024). "Additionally, patients who suffered diabetes for a longer time often are more in need of receiving insulin treatments, for obvious reasons." (PMID 38435625, 2024). "Diabetes mellitus is characterized by a lack of or insufficient amount of insulin, resulting in loss of blood glucose homeostasis and chronic hyperglycemia." (PMID 38346191, 2024).
diabetes (continued). "Whether the prerequisite daughter will progress to diabetes requires further follow-up, and the early initiation of good control of insulin and metabolic indicators may be beneficial to delay the progression of the disease." (PMID 37204622, 2024). "The in-hospital diabetes teams have operational algorithms to titrate insulin in both arms." (PMID 38711112, 2024). "In an RCT with adults who had obesity and insulin resistance (pre-diabetes), insulin sensitivity was assessed by hyperinsulinemic-euglycemic clamps and improved after 6 weeks of daily blueberry intake (equivalent of 300 g fresh blueberries; providing 668 mg anthocyanins)." (PMID 38919390, 2024). "Indeed, a very important finding of this research was that glycemia was affected by age, sex, adiposity markers, inflammation, liver and insulin markers in people with prediabetes in an independent manner to that evidenced in diabetes." (PMID 39767255, 2024). "The observed association of social vulnerability with glycaemic phenotypes (Dim1) may be mediated by different access to innovative care (such as automated insulin delivery systems), lower diabetes education and diabetes self-management skills." (PMID 38780786, 2024). "Moreover, 4687 (56.7%) were diagnosed with type 2 diabetes mellitus, and 3632 (43.9%) received insulin therapy." (PMID 38218835, 2024). "Insulin pumps are equipped with different characteristics to improve their mobility, disposability, and connection in order to meet the varied requirements of patients who are controlling diabetes." (PMID 39065641, 2024). "However, of the patients with diabetes requiring insulin at baseline, three (60.0%) had a toxicity leading to omission of at least one cycle of chemotherapy." (PMID 38392055, 2024). "Moreover, the Royal College of Nursing, Trend UK, and Diabetes UK demonstrated that significantly reduced levels of insulin error and therefore reduced LOS were observed with DSNs, particularly in registered nurse prescribers." (PMID 38338237, 2024). "This could result in the development of diabetes in previously undiagnosed patients and explain the need for insulin in severe situations." (PMID 39995847, 2024). "We have been studying the effects of diabetes on the aging process in diabetic mice and found that the activity of Akt, a key molecule for insulin signaling, is decreased in diabetic and aging mice, resulting in loss of muscle mass mainly in fast-twitch muscles, similar to sarcopenia in humans." (PMID 39513056, 2024). "This study aimed to identify the suitable induction protocol to produce highly qualified insulin producing cells (IPCs) from human adipose tissue derived stem cells (ADSCs) and evaluate the efficacy of the most functionally IPCs in management of diabetes mellitus (DM) in rats." (PMID 39424616, 2024). "This theory is further supported by our data as higher leptin (or body fat) levels were important for predicting low NT-proBNP levels in women with normal glucose tolerance, while impaired insulin sensitivity was the most important factor after developing prediabetes/diabetes." (PMID 39097697, 2024). "Increased risk of cancer due to hyperinsulinemia may be caused by both endogenous (prediabetes, metabolic syndrome, obesity, T2DM) and exogenous hyperinsulinemia (insulin therapy for diabetes mellitus)." (PMID 38392069, 2024). "Given the fact that obesity and insulin secretion are interdependent, any correlation of hsa-miR-320a-3p seen with key glycemic and obesogenic targets may indicate its parellel role in diabetes and other metabolic complications." (PMID 39464889, 2024). "The combination strategy leverages the multiple mechanisms of tirzepatide and the stable glucose-lowering effect of basal insulin, providing a comprehensive management plan for diabetes patients, thereby maximizing treatment efficacy (as demonstrated in SURPASS-5 and SURPASS-6)." (PMID 39263564, 2024).
diabetes (continued). "Therefore, it is mandatory to address the efficacy and safety of insulin Icodec in various insulin regimens, particularly the basal-bolus regimen, in both types of diabetes, which was the aim of our systematic review." (PMID 39200316, 2024). "Diabetes mellitus, a metabolic disorder characterized by impaired glucose homeostasis and hyperglycemia, is caused by a lack of insulin responsiveness or production." (PMID 39062777, 2024). "Oral 8 mg insulin (ORMD-0801) was recently shown to be effective in patients with type 2 diabetes mellitus (T2DM) without increasing the risk of hypoglycaemia." (PMID 39131144, 2024). "Female patients were older and had a longer duration of diabetes, higher proportion of hypertension, which may increase the possibility of using of insulin, CCBs, ACEI/ARBs in these patients." (PMID 39511977, 2024). "The aberrant activation of signaling cascades mediated by insulin and the insulin-like growth factor (IGF) family has been implicated in the pathophysiology of numerous ailments, including diabetes, cancer, obesity, neurodegenerative disorders, and musculoskeletal conditions." (PMID 38726016, 2024). "These alterations may pose significant cardiometabolic risks to these women, particularly hypertension, resistance to insulin action, type 2 diabetes mellitus, dyslipidemia, and cardiovascular diseases." (PMID 38732514, 2024). "(A) Impaired metabolism through the insulin pathway and others, (B) inflammation and oxidative stress and (C) cerebral vessel pathology in diabetes might all contribute to CI, its subtypes, or mixed types." (PMID 39767690, 2024). "Thus, the inclusion of EGCG in medical nutrition therapy would contribute to achieving glycemic control and improving insulin sensitivity in individuals with diabetes." (PMID 39770980, 2024). "Since then, insulin has evolved from an extracted hormone to sophisticated synthetic analog formulations and regenerative therapies, revolutionizing diabetes management and improving patient outcomes marked by significant milestones in biomedical research and therapeutic innovation." (PMID 39734941, 2024). "The proposed intervention has the potential to significantly transform the present situation of diabetes mellitus pharmacotherapy, particularly considering the substantial number of individuals, estimated to be around 200 million, who are in need of insulin therapy." (PMID 38255888, 2024). "Diabetes progression status was assessed by the number of oral GLDs or use of insulin." (PMID 38366387, 2024). "This meta-analysis was performed to obtain a comprehensive overview of the differences between once-weekly basal insulin (including icodec and basal insulin Fc) and once-daily basal insulin (including glargine and degludec) in patients with type 1 and type 2 diabetes mellitus." (PMID 39629047, 2024). "Diet plays a critical role in the management of diabetes among those who are taking insulin." (PMID 39458437, 2024). "To conclude, Mg supplementation not only has a potentially beneficial role, improving glucose parameters in people who already suffer from diabetes, it may also improve insulin-sensitivity parameters in patients with increased diabetic risk." (PMID 39685901, 2024). "Type 1 diabetes mellitus (T1DM) is an immune system infection, and insusceptible assaults result in the obliteration of islet cells, causing islet aggravation related to outright insulin lack." (PMID 38800472, 2024). "Low levels of insulin (0.6 mIU/L) and C-peptide (0.1 ng/mL) indicated insulinogenic diabetes." (PMID 39450164, 2024). "A self-administered questionnaire was developed based on a literature review to assess sociodemographic characteristics and diabetes and insulin knowledge, and validated scales were used to assess self-management (SMOD-A) and psychological well-being (ChilD-S)." (PMID 39160425, 2024).
diabetes (continued). "Therefore, we concluded that reducing the severity of diabetes induction would facilitate achieving insulin independence with a lower transplanted islet mass." (PMID 39070316, 2024). "In previous reports, parasympathetic nerve activity measured by the high‐frequency (HF) component of heart rate variability (HRV) decreased with disease progression and was related to the severity of the abnormal glucose/insulin metabolism in type 2 diabetes mellitus (T2DM)." (PMID 38050866, 2024). "Indeed, prevalent diabetes can vary in duration, exposure to glucose-lowering medications (including insulin), and complications, making it difficult to determine the role of hyperglycemia or insulin resistance per se in lung cancer development." (PMID 38902745, 2024). "Because subjects on insulin were excluded from the analysis, we may reasonably assume that the included persons with diabetes are in the large majority affected by type 2 diabetes." (PMID 38169110, 2024). "Therefore, stimulation of the GLP-1 receptor is likely to enhance insulin secretion strongly in Japanese patients with diabetes, and incretin enhancers are beneficial for treating Japanese patients with diabetes." (PMID 39610482, 2024). "On the other hand, inhibitors of the DPP-IV enzyme are used in the treatment of diabetes because they increase the half-life of incretins, which are peptide hormones that stimulate more than 50% of insulin secretion, especially the hormone glucagon peptide (GLP-1)." (PMID 38337933, 2024). "Frameworks are limited by their domain or condition area, meaning a framework may be suitable to assess all digital health apps (such as Enlight), but not pick up on a condition area that is specific to quality issues, such as insulin intake for diabetes apps." (PMID 39388698, 2024). "In conclusion, this large, nationwide study of MA patients with diabetes found that insulin refill lapses were more likely to occur for those with T1D who paid more than $35 per 30‐day supply of insulin on average during the follow‐up year and more than $20 for those with T2D." (PMID 36992575, 2024). "The initial diabetes management consisted of oral medication, and later included insulin." (PMID 38475930, 2024). "Regarding concomitant drug use for diabetes, alpha-glucosidase inhibitors, dipeptidyl peptidase-4 inhibitors, glinides, glucagon-like peptide-1 agonists, and insulin were more commonly used as the albuminuria severity increased, while biguanides were less frequently used." (PMID 37955878, 2024). "Disruptions in calcium homeostasis may contribute to insulin dysfunction and disturbances in glucosehomeostasis, potentially playing a role in the development of type 2 diabetes mellitus (T2DM)." (PMID 38352911, 2024). "Therefore, the detection of insulin levels is crucial in clinical diagnosis for the surveillance of pre-diabetes and diabetes, as well as the prevention of its complications." (PMID 39091901, 2024). "Diabetes mellitus is a chronic metabolic disease characterised by a disorder of glucose metabolism resulting from the consistent presence of beta-cell dysfunction leading to insufficient insulin secretion, reduced insulin sensitivity, or both." (PMID 39872315, 2024). "For endocrine-metabolic comorbidities qualifying as moderate or severe by CIRS, 41% of KCCC patients had diabetes treated with oral agents or insulin, 10% had dyslipidaemia requiring medication, and 11% had other endocrine-related problems (e.g., thyroid disorders)." (PMID 38741031, 2024). "Indeed, compared to the other dementia types, in the present study the proportions of people with vascular dementia or mixed (Alzheimer’s and vascular) dementia having hypertension, peripheral vascular disease, and diabetes controlled with insulin were higher." (PMID 38182985, 2024).
diabetes (continued). "Finally, HCL systems enable users to configure various modes (e.g., to accommodate changing insulin needs with exercise), and allow others (e.g., parents) to co-monitor blood glucose levels of the individual managing diabetes via smartphone." (PMID 38846748, 2024). "Although the diabetes nurse was found to have a positive effect on timely basal insulin-initiation, this was not the case for the risk of postponed basal insulin-initiation." (PMID 38116986, 2024). "Equil patch insulin pump is a reliable tool for glycemic management of diabetes mellitus." (PMID 38599884, 2024). "Finally, 1 participant also spoke about the need to keep diabetic patients up to date on the latest research being done on diabetes, insulin, new diabetic medicines, and so forth, as it gives them hope for the future." (PMID 38523416, 2024). "The report that the system generates is invaluable to the HCPs, the diabetic patients and their caregiver because it can show the consequences of behaviors such as missing or late insulin doses and inaccurate carbohydrate counting thus providing an opportunity for targeted diabetes education." (PMID 39411309, 2024). "Some of the leading systems include the Medtronic MiniMed 780G (Medtronic, Dublin, Ireland), Tandem Diabetes Care's t:slim X2 with Control-IQ (Tandem Diabetes Care, Inc., San Diego, CA), and the Omnipod 5 Automated Insulin Delivery System (Insulet Corporation, Acton, MA)." (PMID 39006724, 2024). "Also, 64.6% of them used insulin in treatment, and 78.7% of them have complications from diabetes and 76.4% of them suffer from chronic diseases, 55.6% of them take other medication." (PMID 38724979, 2024). "Understanding the impairment of diabetes-related insulin signaling induced by obesity may lead to better pharmacological strategies not only for the treatment but also for the prevention of obesity and diabetes." (PMID 39275320, 2024). "Adiponectin could increase fat metabolism, control insulin sensitivity, modify homeostasis, and regulate glucose tolerance to protect individuals from diabetes." (PMID 37927197, 2024). "Understanding the mechanisms behind iron-related oxidative stress and its impact on insulin secretion could provide valuable insights into the prevention and management of diabetes and CVD." (PMID 39179569, 2024). "Also, Bağrıaçık reported that education provided based on Pender’s HPM helped individuals with diabetes develop a positive attitude towards insulin treatment." (PMID 39030532, 2024). "Achieving an optimal HRQOL in T1DM requires a comprehensive treatment approach that encompasses insulin therapy, carbohydrate counting as part of dietary management, regular physical exercise, self-monitoring, and effective diabetes education to handle everyday challenges and exceptional situations." (PMID 38999807, 2024). "Diabetes is a chronic disease characterized by hyperglycemia and an alteration in carbohydrates, fats, and protein metabolism due to a shortage in the secretion of insulin or its impaired action." (PMID 39202972, 2024). "Hyperglycemia refers to high blood glucose levels caused by metabolic disturbances affecting the pancreatic β-cells, involving type 1 diabetes mellitus (insufficient insulin synthesis by the pancreas) and type 2 diabetes mellitus (ineffective action of insulin)." (PMID 38893333, 2024). "Insulin-stimulated signaling pathways regulate insulin receptor substrate (IRS) activity in various tissues, including muscle and pancreatic beta cells, and have been identified as a pathogenic factor in diabetes onset (Yiannakouris, 202)." (PMID 38694942, 2024). "Finally, we attempted to rescue the diabetes‐like phenotype of Ins2‐Tipe1BKO mice by overexpressing Gαs using an adenovirus in vitro, and the results showed that the insulin secretion level stimulated by high‐glucose concentrations was partially rescued." (PMID 38417114, 2024).